NR3C1 (nuclear receptor subfamily 3 group C member 1)
Diseases named in the same sentence as NR3C1 in open-access papers (continued):
Sharing a sentence is not in itself a finding about the gene and the disease.
systemic lupus erythematosus (5 papers, 2009 to 2023). An autoimmune multi-organ disease typically associated with vasculopathy and autoantibody production. "The SNV (rs4607376) in nuclear receptor subfamily 3 group C member 1 gene (NR3C1), which is a glucocorticoid receptor, was previously reported in only one clinical study and it was related with systemic lupus erythematosus." (PMID 33402871, 2020).
autism (4 papers, 2012 to 2025). Persistent deficits in social interaction and communication and interaction as well as a markedly restricted repertoire of activity and interest as well as repetitive patterns of behavior. "From the total set of genes constituting the NBC, 233 candidates occur in at least 5 sibling conditions, 74 are present in 7 or more siblings, 29 in 8 or more, 13 in 9 autism siblings, 3 in 10 autism sibling disorders (MAGI2, NR3C1, SLC1A2) and one (SLC1A2) present in 12 siblings." (PMID 28427329, 2017).
breast tumor (4 papers, 2021 to 2025). "For instance, DNAm of the NR3C1 gene, which encodes the glucocorticoid receptor, has been linked to early-life adversity and observed in breast tumor tissues." (PMID 40796574, 2025).
cardiomyopathy (4 papers, 2019 to 2025). A disease of the heart muscle or myocardium proper. "Based on the findings of cell type-specific regulatory activity, the most active TFs in each of the 4 cardiomyopathy fibroblast subpopulations, including NR3C1 (C0 THBS4+ Fibroblasts), KLF4 (C1 LINC01133+ Fibroblasts), FOSB (C2 FGF7+ Fibroblasts), FOS (C3 AGT + Fibroblasts)." (PMID 38799173, 2024).
polycystic ovary syndrome (4 papers, 2014 to 2024). A disorder that manifests as multiple cysts on the ovaries. "NR3C1 appears to be implicated in polycystic ovarian syndrome through modulating the stress response." (PMID 38217051, 2024). "It was reported that variants in NR3C1 may have an influence on gonadotropin levels in women with anovulatory polycystic ovary syndrome (PCOS)." (PMID 24741566, 2014).
preeclampsia (4 papers, 2014 to 2025). Preeclampsia is a hypertensive disorder of pregnancy that is characterized by new-onset hypertension with proteinuria presenting after 20 weeks of gestation, and depending on mild or severe forms may initially present with severe headache, visual disturbances, and hyperreflexia. "A case-control study of postpartum Mexican women (N = 40) compared women with preeclampsia and normotensive women and found differential methylation patterns in promotor regions of genes, including NR3C1 among women with preeclampsia, suggesting a regulatory role in response to stress in pregnancy." (PMID 37987302, 2023). "Cardiac gene expression of Vcam, Edn1, Ccr2, Ctgf, Tgfb1, Tgfb2, Tgfb3, Bnp, Cybb, Mmp2, Mmp9, Timp1, Camk2a, Slc9a1, Nr3c2, and Nr3c1 was not different between mice who had a normal pregnancy and mice who had a preeclampsia-like pregnancy at 5 or 10 weeks postpartum (respectively)." (PMID 40425613, 2025).
Adrenal Incidentalomas (3 papers, 2016 to 2021). "Mutation in the NR3C1 gene, encoding for the glucocorticoid receptor, has also been identified in 5% of a series of patients presenting with bilateral adrenal incidentalomas." (PMID 34680514, 2021).
allergic asthma (3 papers, 2013 to 2024). A asthma with a basis in a pathological type I hypersensitivity reaction. "Given existing knowledge of the role of Nr3c1 in allergic asthma, we tested the effect of DEX, a steroid that binds to Nr3c138, in our animal model on both the disease phenotype and super-connector gene expression." (PMID 27097888, 2016).
bulimia nervosa (3 papers, 2014 to 2022). A disorder characterized by recurrent episodes of binge-eating over which the individual feels a lack of control; these episodes of binge-eating are followed by recurrent compensatory behavior to prevent weight gain, usually self-induced vomiting. "The hyper-/hydroxy-/methylation of NR3C1 induced by chronic alcohol consumption preferentially targets the exon 1H, while the 1F and 1C exon variant are reported as differentially methylated in suicidal patients and in women with bulimia nervosa, respectively." (PMID 31239533, 2021).
clear cell renal cell carcinoma (3 papers, 2023 to 2025). "NR3C1 encodes the glucocorticoid receptor and NR3C1 knockdowns have been shown to inhibit the proliferation and migration of clear cell renal cell carcinoma in laboratory and mouse model studies although no sex biases have been reported." (PMID 41024254, 2025).
Crohn disease (3 papers, 2020 to 2024). A gastrointestinal disorder characterized by chronic inflammation involving all layers of the intestinal wall, noncaseating granulomas affecting the intestinal wall and regional lymph nodes, and transmural fibrosis. "Other positive correlation, T2D-AD associated drugs included budesonide (corticosteroid for Crohn’s disease) and mometasone (steroid for skin discomfort), both of which are glucocorticoid receptor agonists with the target of NR3C1." (PMID 39713369, 2024).
glomerular diseases (3 papers, 2021 to 2025). "Studies of the NR3C1 in glomerular diseases are limited and provide contradictory results." (PMID 34831409, 2021). "However, the role of NR3C1 in the pathogenesis of glomerular diseases in adults have not been studied and is not fully understood." (PMID 34831409, 2021).
lipid metabolism disorders (3 papers, 2023 to 2025). "Then, lipidomic and transcriptomic sequencing showed that lipid metabolism disorders, ER stress, and mitophagy genes were enriched in the sh-NR3C1 group." (PMID 37807060, 2023). "Secondly, this study confirmed through lipidomic sequencing that there is lipid metabolism disorder in ccRCC cells after knocking down NR3C1." (PMID 37807060, 2023).
lung disease (3 papers, 2007 to 2014). "Therefore, it appears that the correct approach to the analysis of the role of SNPs in the etiology of pulmonary diseases is a multifactorial interpretation of the function of NR3C1 gene polymorphisms in the pathogenesis of obstructive syndromes." (PMID 23407653, 2013).
major depressive episode (3 papers, 2019 to 2023). "For example, reviewing the literature has highlighted the involvement of methylation of the NR3C1 gene (epigenetic modification of this gene coding for a glucorticoid receptor) in the predisposition to a major depressive episode in a setting where there is chronic early stress." (PMID 37628343, 2023). "For example, 48 hours’ intrapartum stress may result in early life stress (ELS), predisposing an adolescent to a major depressive episode (MDD), through adverse epigenomic modulation with DNA methylome impairing the glucocorticoid receptor gene (NR3C1) expression." (PMID 31717711, 2019).
multiple sclerosis (3 papers, 2013 to 2020). A progressive autoimmune disorder affecting the central nervous system resulting in demyelination. "The aim of the present study was to investigate the role of lncRNA GAS5 and its downstream target Nuclear Receptor Subfamily 3 Group C Member 1(NR3C1) in the pathogenesis of multiple sclerosis (MS), and to define the role of GAS5 in the regulation of NR3C1 expression." (PMID 30276165, 2018).
nephrotic syndrome (3 papers, 2011 to 2019). A collection of symptoms that include severe edema, proteinuria, and hypoalbuminemia; it is indicative of renal dysfunction. "To date, a few studies investigated the role of NR3C1 polymorphisms on the glucocorticoid response in pediatric patients with nephrotic syndrome." (PMID 29549463, 2019).
pituitary tumor (3 papers, 2011 to 2023). A benign or malignant neoplasm affecting the pituitary gland. "Due to a weak relationship with patients characteristics it is difficult to indicate any clinical usefulness of testing NR3C1 or NR3C2 expression but our data support the clinically relevant roles of the receptors expression levels in functioning corticotroph pituitary tumors." (PMID 37065760, 2023).
prostate tumors (3 papers, 2018 to 2021). "NR3C1 was consistently downregulated in prostate tumors compared to normal prostate tissues in 9 of the 10 datasets." (PMID 30305646, 2018).
psychological distress (3 papers, 2016 to 2025). "The glucocorticoid receptor plays a critical role in HPA responses to stress through negative feedback on glucocorticoid release, and exposure to prenatal psychological distress has been associated with increased offspring NR3C1 DNA methylation." (PMID 26940835, 2016). "Interestingly, there are reports that maternal psychological distress affects DNA methylation in the corticotropin-releasing hormone and glucocorticoid receptor gene (NR3C1) in neonatal cord blood, and brain-derived neurotrophic factor in infants." (PMID 38418579, 2024).
Tinnitus (3 papers, 2021 to 2026). Tinnitus is an auditory perception that can be described as the experience of sound, in the ear or in the head, in the absence of external acoustic stimulation. "The glucocorticoid receptor NR3C1 and its interaction with FKBP5, a glucocorticoid receptor-induced co-chaperone, appear to be of particular importance for the emotional aspects of tinnitus." (PMID 41751990, 2026).
acute graft versus host disease (2 papers, 2018 to 2025). A syndrome of immunologically mediated tissue damage that may occur following an allogeneic transplant, usually affecting the skin, liver, and GI tract. "Among 30 patients who developed grades III to IV acute GVHD treated with glucocorticoids, recipient NR3C1 rs33388 TT genotype was associated with significantly lower overall survival compared with AT/AA (24.4% vs. 63.5% at 5 years, P = 0.044)." (PMID 41264074, 2025).
bronchopulmonary dysplasia (2 papers, 2014 to 2021). Bronchopulmonary dysplasia is a chronic respiratory disease that results from complications related to lung injury during the treatment of infant acute respiratory distress syndrome in low-birth-weight premature infants or from abnormal lung development in older infants. "Neonates exposed to glucocorticoids in utero and carriers of the genetic variant NR3C1 rs6195 have poorer language and cognitive abilities and an increased risk of bronchopulmonary dysplasia." (PMID 33981330, 2021).
colorectal adenoma (2 papers, 2007 to 2023). An adenoma that arises from the colon or rectum. "In 17 colorectal adenomas and paired normal mucosa, NR3C1 (a gene that encodes the GCs receptor (GR)) was reported as a key component of tumor formation." (PMID 36918865, 2023).
conduct disorder (2 papers, 2018 to 2025). A disorder diagnosed in childhood or adolescence age group characterized by aggressive behavior, deceitfulness, destruction of property or violation of rules that is persistent and repetitive, and within a one year period. "Some genetic predispositions should be taken into consideration, as glucocorticoid receptor NR3C1 variants among ADHD children were reported to have a moderate influence on ADHD severity and the occurrence of concurrent conduct disorder." (PMID 40869288, 2025).
dependence (2 papers, 2015 to 2026). "In contrast, Nr3c1/GR activity increases progressively during alcohol exposure and dependence in the VTA and NAc core, while in the NAc shell, Nr3c1/GR activation is seen only after the transition to dependence." (PMID 25886852, 2015).
Ewing sarcoma (2 papers, 2023 to 2024). A small round cell tumor that lacks morphologic, immunohistochemical, and electron microscopic evidence of neuroectodermal differentiation. "Expression of NR3C1 and AR was higher in DSRCT PDXs as compared to Ewing sarcoma and CIC-DUX4 PDXs." (PMID 38575753, 2024).
Fibroadenoma (2 papers, 2021 to 2025). A benign tumor of the breast characterized by the presence of stromal and epithelial elements. "Among inflammatory markers, NR3C1 showed lower expression in healthy mammary tissue from the Diet group but was significantly higher in fibroadenomas and lower in cancers from the Control group." (PMID 40806434, 2025).
Glucocorticoid Deficiency (2 papers, 2017 to 2025). "Sequence and copy number variation analysis of NR3C1 using proprietary software (Blueprint Genetic Glucocorticoid Deficiency Panel) demonstrated the patient to be heterozygous for a variant in the NR3C1 gene c.1322G > C, p.(Cys441Ser)." (PMID 39850725, 2025).
Hearing impairment (2 papers, 2015 to 2021). A decreased magnitude of the sensory perception of sound. "The findings of this study show that recovery effect of DA9801 in the hearing impairment produced by DM model could be elicited by inducing NGF expression through Nr3c1 protein expression via Akt transformation." (PMID 25878713, 2015).
hyperandrogenism (2 papers, 2011 to 2024). Excessive secretion of androgens from the adrenal glands or gonads. "The network pharmacology analysis report found 988 PCOS-related genes, 108 hyperandrogenism-related genes, and 377 oligomenorrhea-related genes, and we finally shortlisted 5 common genes in PCOS, hyperandrogenism, and “oligomenorrhea”: NR3C1, PPARG, FOS, CYP17A1, and H6PD." (PMID 39294254, 2024).
insomnia (2 papers, 2022). A sleep disorder characterized by difficulty in falling asleep and/or remaining asleep. "These high-degree protein targets may be the key targets such as neurotrophic receptor tyrosine kinase 1, nuclear receptor subfamily 3 group C member 1, cyclin D1, erb-B2 receptor tyrosine kinase 2, and account for the essential therapeutic effects of CWT on insomnia." (PMID 36110515, 2022).
internalizing disorder (2 papers, 2018 to 2021). A type of mental or behavioral disorder, typically in children and young adults, with symptoms including depression, anxiety and withdrawal. "Overall methylation levels of NR3C1 exon 1 in blood and saliva DNA probes were associated with higher levels of internalizing disorders." (PMID 30510522, 2018).
lung adenocarcinoma (2 papers, 2015 to 2018). A carcinoma that arises from the lung and is characterized by the presence of malignant glandular epithelial cells. "JUN and NR3C1 were detected by both differential interactions and by differential expression, increasing their possibility to be correlated with lung adenocarcinoma." (PMID 26402252, 2015). "It was thus inferred that JUN, NR3C1, and GRB2 were most likely to be new candidate lung adenocarcinoma-related genes." (PMID 26402252, 2015).
migraine (2 papers, 2022 to 2024). "NR3C1 (glucocorticoid receptor) has effects on inflammatory responses, and especially has a wide distribution in neurons and neuroglia, which shows the active role of NR3C1 in migraines." (PMID 36079577, 2022).
muscular dystrophies (2 papers, 2022 to 2024). "Here, we knocked out the glucocorticoid receptor (GR, encoded by Nr3c1) specifically in myofibers and cardiomyocytes within wild-type and mdx52 mice to dissect its role in muscular dystrophy." (PMID 38770680, 2024). "Thus, defining the role of the glucocorticoid receptor (GR; encoded by Nr3c1 in mice) in the natural etiology of muscular dystrophy will help to clarify the mechanism of action for this drug class and to develop improved treatments for muscle diseases featuring chronic inflammation." (PMID 38770680, 2024). "Three of these genes, ETS1, NR3C1 and JARID2, are common in all five muscular dystrophies with no previous association with any of the five muscular dystrophies based on bibliography." (PMID 35388741, 2022).
osteosarcoma (2 papers, 2011 to 2022). A usually aggressive malignant bone-forming mesenchymal neoplasm, predominantly affecting adolescents and young adults. "Furthermore, several NRs such as NR4A2, NR4A1, and NR3C1 have been found to be differentially expressed in most types of DEGs among metastasis, primary, and recurrent osteosarcomas." (PMID 35965537, 2022). "Furthermore, several NRs such as NR4A2, NR4A1, and NR3C1 have been found to be differentially expressed in most types of DEGs among metastasis, primary, and recurrent osteosarcoma." (PMID 35965537, 2022). "In “Myeloid”, differentially expressed NRs such as NR4A2, NR4A1, NR3C1, RXRA, NR1D2, PPARD, and RARA were identified among metastasis, primary, and recurrent osteosarcoma tissues." (PMID 35965537, 2022). "In “Pericyte”, differentially expressed NRs such as NR4A1, NR3C1, NR2F2, NR2F1, NR1H2, and ROR were detected among metastasis, primary, and recurrent osteosarcoma tissues." (PMID 35965537, 2022). "Based on our analysis, we found that several NRs including NR4A2, NR4A1, NR3C1, NR2F6, and NR2F2 were differentially expressed in osteoblastic cells among metastasis, primary, and recurrent osteosarcomas." (PMID 35965537, 2022).
ovarian tumors (2 papers, 2011 to 2025). "It was further verified that NR3C1 has a high diagnostic ability in differentiating the two ovarian tumors." (PMID 40959664, 2025).
panic attack (2 papers, 2020 to 2024). "The purpose of this study was to investigate the effects of escitalopram on the peripheral expression of hypothalamic-pituitary-adrenal (HPA) axis-related genes (FKBP51, HSP90, NR3C1 and POMC) and HPA-axis hormones in patients with panic disorder (PD)." (PMID 38600448, 2024).
pneumonia (2 papers, 2021 to 2025). An acute, acute and chronic, or chronic inflammation focally or diffusely affecting the lung parenchyma, caused by an infection in one or both of the lungs (by bacteria, viruses, fungi, or mycoplasma.). "We also found previously that a high-calorie diet will cause serum ACTH and CORT to decrease and expression levels of hypothalamus Nr3c1 and Nr3c2 proteins to decrease in juvenile rats with LPS-induced pneumonia." (PMID 40724811, 2025).
acne (1 paper, 2024). An inflammatory process of the sebaceous glands which is characterized by comedones, nodules, papules and/or pustules on the skin. "We noted that the expression of PPAR-γ, SREBP-1, 11βHSD and NR3C1 in the acne-like mouse ear skin lesions were obviously higher than those observed in the normal mice, whereas GA significantly down-regulated the expression of these proteins." (PMID 38792208, 2024). "Indeed, in this study, the experimental results revealed that the sebogenesis-related factors such as SREBP-1, PPAR-γ, NR3C1 and 11βHSD obviously increased, resulting in the lipid accumulation in P. acnes-induced acne-like ear skin lesions." (PMID 38792208, 2024).
age-related macular degeneration (1 paper, 2022). Age-related loss of vision in the central portion of the retina (macula), secondary to retinal degeneration. "In a model of age-related macular degeneration, miR-382-5p has been described to negatively regulate PTEN and subsequently activate the AKT/mTOR pathway, whereas NR3C1 acted as a miR-382-5p sponge, consequently regulating this pathway." (PMID 35884935, 2022).
amyloid (1 paper, 2022). "As expected, clustered formations became random closer to amyloid plaques in both Nr3c1+/+-APP/PS1 and Nr3c1ki/ki-APP/PS1 genotypes (P < 0.05); clustered eliminations were random in the proximal and intermediate zones except for Nr3c1ki/ki-APP/PS1 mice (P = 0.04)." (PMID 35733193, 2022).
Arrhythmia (1 paper, 2026). Any cardiac rhythm other than the normal sinus rhythm. "In parallel, 902 arrhythmia-related genes were retrieved, yielding 24 overlapping targets, among which five hub genes (PIK3CA, CREBBP, NR3C1, SCN10A, and KCNA5) were identified." (PMID 42292832, 2026).
bladder tumor (1 paper, 2024). "In agreement with our PCa data, FOXA1 OE resulted in a significant decrease while FOXA1 KO manifested in a significant increase of NR3C1 expression in bladder tumor organoids." (PMID 38015476, 2024).
childhood asthma (1 paper, 2021). "NR3C1 could thus act as a risk factor for severe OM through perturbation of endogenous regulation of inflammation, as seen in childhood asthma." (PMID 33693626, 2021).